PDC (phosducin)
Diseases named in the same sentence as PDC in open-access papers (continued):
Sharing a sentence is not in itself a finding about the gene and the disease.
infection (continued). "We, therefore, concluded that IC-mediated pDC activation represents the physiological immune response to infection." (PMID 24904586, 2014). "We found that pDC in the lumbar lymph nodes, which drain the vagina, were efficiently depleted at the time of infection." (PMID 24204273, 2013). "The VPR-infected SK-6 cells were treated for the last 2 h of infection followed by removal of the inhibitor by a wash step before co-culture, to avoid direct effects of the drugs on pDC and to enable efficient virus replication before co-culture." (PMID 23785283, 2013). "First, pDC depletion resulted in dramatically lower numbers of Tregs in the lung, the local infection site and also in the draining lymph nodes." (PMID 24386207, 2013). "It is notable that pDC-depleted mice had pronounced T cell responses, but markedly increased levels of infection in the lung." (PMID 24386207, 2013). "This is supported by the data that the reduction of Tregs and IL-10 production in pDC depleted mice is correlated with histologic findings showing massive cellular infiltration and extensive tissue damage in their lungs after infection." (PMID 24386207, 2013). "In particular, it is critical to understand how pDC modulate the T cell responses which is a key determinant in influencing the infection outcome." (PMID 24386207, 2013). "Infection was associated with a marked increase and then decline in the number of blood pDC which then steadily returned to pre-infection levels by around day 30 post infection, and these kinetics were unaffected by DV056 treatment." (PMID 23935491, 2013). "Although a decrease in pDC numbers occurred, we find that the pDC present during infection of aged mice are more suppressive, as observed after pDC depletion in aged mice CD8 T cell responses are partially recovered." (PMID 21695169, 2011). "In this culture system, only R5 exposed thymic pDC were able to transfer productive infection to CD3hi thymocytes." (PMID 21639903, 2011). "We find that pDC are lost from blood and peripheral lymph nodes early in SIV infection despite massive mobilization and recruitment, associated with pDC activation, infection and death in lymph nodes." (PMID 19424421, 2009). "We found that pDC were present in normal numbers in bone marrow but were lost from blood and lymph nodes within 14 days of intravenous infection." (PMID 19424421, 2009). "We show that pDC are lost from blood and peripheral lymph nodes within 14 days of infection, despite a normal frequency of pDC in bone marrow." (PMID 19424421, 2009). "The overall loss of pDC from lymph nodes despite their massive recruitment strongly suggests that pDC are dying in these tissues during infection." (PMID 19424421, 2009). "In any case, the possibility to harness pDC functions in the clinic to help treat infections with herpesviruses in immunocompromised individuals is promising." (PMID 21994554, 2009). "We conclude that migration and death both contribute to pDC depletion, with influx into lymph nodes bringing cells into an environment favoring their death by infection or apoptosis." (PMID 19424421, 2009). "One strength of this data set is that it allows us to explore how pDC gene expression may change over time throughout infection." (PMID 39920132, 2025). "This was observed both in the MDM-pDC coculture setup and after direct infection of pDC." (PMID 35758667, 2022). "Since pDC are of major importance in rapidly producing massive amounts of IFNα early in infection, our data suggest that production of L-particles before H-particles might represent a powerful immune evasion mechanism during the initial stages of infection." (PMID 34843605, 2021). "Furthermore, we show that there is impaired pDC functionality in untreated individuals from as early as 1-month post-infection, whereas responses to antigenic stimulation are preserved at pre-infection levels with early ART commencement." (PMID 34630420, 2021).
infection (continued). "The observed differences might reflect exhaustion of pDC during infection with the highly virulent strain." (PMID 32733474, 2020). "Based on the fact that pDCs are affected by single HIE and that LC-Plasma activates pDC and improves URTI, we hypothesized that ingestion of LC-Plasma would maintain pDC activity and suppress infection morbidity even during consecutive HIE." (PMID 30071871, 2018). "To further examine the role of IFN-I, we specifically depleted pDC before infection." (PMID 28337202, 2017). "Unexpectedly, we found pDC gene expression to be largely stable in early sub-microscope infection." (PMID 28572564, 2017). "The beneficial or detrimental effects of pDC and type I IFNs in infection may depend on the timing of their action." (PMID 28572564, 2017). "At day 82 of infection all control mice were dead and four pDC-depleted mice were still alive." (PMID 27992577, 2016). "Reduced hepatic fungal loads were observed in pDC-depleted mice only at week 8 after infection." (PMID 27992577, 2016). "In addition, a reduced expression of IDO mRNA in the lungs of pDC-depleted mice was detected at all post-infection periods." (PMID 27992577, 2016). "This suggests that in response to YPIII infection pDC may migrate from the spleen to the Peyer’s patches." (PMID 25075520, 2014). "In addition we show that pDC are strongly activated during the acute infection and this activation persists during chronic infection, although to a lower level than during acute infection." (PMID 24497833, 2014). "Similar to HIV-R3A infection, JR-CSF replication was increased in pDC-depleted mice (about 5-fold)." (PMID 25077616, 2014). "However, pDC depletion during chronic infection decreased infection-induced T cell apoptosis and increased T cell numbers in lymphoid organs." (PMID 25400632, 2014). "The lungs of pDC depleted mice had significant accumulation of T cells following Cpn infection." (PMID 24386207, 2013). "Thus, pDC mediated functions can manifest in different ways in host immune protection with respect to the type of pathogens and infections." (PMID 24386207, 2013). "However, during late stage of infection, the pDC depleted mice had impaired bacterial clearance and prolonged inflammation in the lungs." (PMID 24386207, 2013). "It will be important to determine whether TLR7- and TLR9-driven activation of pDC plays any role in immune activation in the chronic stages of infection when disease is manifest." (PMID 23935491, 2013). "We then examined separately the gene expression of mDC and pDC in response to MVA-C infection." (PMID 22536391, 2012). "However, while IFN-γ and IL-6 were present at similar concentrations compared with control mice at days 14 and 21 post infection, IL-12p40 was significantly increased at day 21 in pDC-depleted animals." (PMID 23119083, 2012). "The level of pDC increased again and fluctuated around baseline at the late stage of infection." (PMID 21118577, 2010). "However, the precise spatiotemporal dynamics of pDC behavior in vivo at steady state and during infection or inflammation, and which cells and molecular events may regulate these events still remain poorly understood." (PMID 36278864, 2022). "However, as TLR stimulation opposes GC induced apoptosis, it is unclear whether increased GC levels during infection would ultimately result in increased pDC apoptosis in vivo and so further study will be needed to evaluate this." (PMID 34578420, 2021). "Therefore, the strength of pDC activation during the very first steps of infection could modulate the global immune response to LASV." (PMID 30901952, 2019). "Therefore, it is possible that multiple factors induced by FL and burn injury may act synergistically to induce these beneficial, pDC-dependent effects on neutrophil responses to infection." (PMID 28228109, 2017). "In addition, pDC depletion did not increase the susceptibility of BALB/c mice after infection with the LD50." (PMID 25954804, 2015).
infection (continued). "pDC regulatory mechanisms may differ with respect to the type of infections." (PMID 24386207, 2013). "In contrast, we found that pDC deficiency resulted in higher IFNγ production in the lungs in the adaptive immune phase following infection, although we did not analyse at early stage of infection." (PMID 24386207, 2013). "Thus, cleavage of VP4 by trypsin is dispensable for both pDC infection and IFNα induction by RRV." (PMID 20532161, 2010). "Moreover, a similar infection rate was observed for splenic pDC, whereas the rate for both CD8+ and C8− cDC was significantly decreased by infection with a lower dose of BCG, further indicating that pDC might be more susceptible to BCG infection than other DC subsets in vivo." (PMID 36977141, 2023). "In order to study the role of pDC in protection against infection, BDCA2-DTR mice in which pDC are depleted upon exposure to DT were challenged orally with C. rodentium." (PMID 31024525, 2019). "After i.p. infection with Mouse hepatitis virus (MHV), pDC depletion by anti-CD317 was accompanied by severely diminished IFNα serum levels." (PMID 31031767, 2019). "In agreement, at week 2 post-infection a reduced frequency of infiltrating CD4+ T cells expressing deactivation or suppressive molecules (CTLA4, GITR, ICOS) were seen in the lungs of pDC-depleted mice." (PMID 27992577, 2016). "We show that the frequency of cDC and pDC increased following FMDV infection and peaked 3 to 4 days post-infection." (PMID 27008425, 2016). "Although moDC can take up HIV-1, they are largely refractory to HIV-1 productive infection, whereas, productive infection of peripheral blood-derived BDCA1+ DC and pDC has been demonstrated." (PMID 24795724, 2014). "In pDC-depleted mice, IL-12p40, IFN-γ, and IL-6 were all reduced at days 3 and 5 after infection compared with control animals." (PMID 23119083, 2012). "Several studies showed a sharp decline of circulating pDC during the acute phase of SIV infection in macaques, which persists throughout the infection." (PMID 20559432, 2010). "The plasma IFNα response at 16 hours post-infection with LDV, as measured by ELISA, was abolished by pDC depletion." (PMID 19568424, 2009). "The intravenous infection of mice with another herpesvirus, HSV-2, also leads to a systemic IFN-I production that is abrogated upon anti-BST2 antibody-mediated pDC depletion." (PMID 21994554, 2009). "In the eye, pDCs reside in the anterior stroma of the cornea, where they make a major contribution to IFN-I production in response to a local infection with HSV-1, as demonstrated by the strong reduction in this response upon local interference with pDC functions." (PMID 38777879, 2024). "Since IFNAR1−/− mice did not lose weight during the course of infection, this suggested that the effect of pDC depletion was not due to lack of type I IFN signaling." (PMID 31024525, 2019). "A direct impact of pDC depletion on type I IFN levels in vivo after infection, however, has not been analyzed in this study." (PMID 31031767, 2019). "It should be noted that the consequence of pDC depletion was specific and not a global reduction in cellular responses to infection as cDCs and overall cellularity in the wound draining lymph nodes were not similarly reduced by prior pDC depletion." (PMID 28228109, 2017). "The observed minimal change in gene expression, together with an absence of activation/maturation phenotype by flow cytometry suggests, circulating blood pDC are not activated, yet remain functional during pre-patent blood-stage infection." (PMID 28572564, 2017). "Although a 2-fold increase in the frequency of CD11c+ cDC and a 3-fold increase in CD4+MHC class II+ pDC was observed, these changes were not statistically different to the levels detected prior to infection." (PMID 27008425, 2016).
infection (continued). "Cell-to-cell infection seems to amplify pDC responses to HIV, however precise mechanisms underlying differences between cell-free and cell-to-cell pDC activation are not clearly defined." (PMID 27082754, 2016). "In accordance, pDC IFN production does not require productive infection by the viral particles since the signaling can be activated by recognition of incoming viral RNA during internalization." (PMID 26295405, 2015). "This corresponded to MOI of less than 10−4 TCID50/enriched pDC, suggesting that stimulation of pDC does not occur by infection of pDC with VRP." (PMID 23785283, 2013). "Our findings suggest that specifically targeting pDC as a therapeutic strategy to reduce immunopathology in HIV infection may have limited benefit, at least in the early stages of infection." (PMID 23935491, 2013). "Thus, it is possible that L. lactis stimulation of pDC results in an integrated immunomodulatory response that may both augment anti-viral immunity and attenuate chronic inflammatory states that may be beneficial for promoting tissue repair after infection-mediated injury." (PMID 22505996, 2012). "Depletion of pDCs in these FLT3L treated mice resulted in reduced inflammation and BALF cell counts 3 days after infection, as well as a significant reduction in IL-12p40, IFN-γ, and IL-6 concentrations in both the BALF and lung homogenates after pDC depletion." (PMID 23119083, 2012). "Notably, 10days after the infection, animals in the DENV/TLR group showed higher frequencies ofactivated pDC when compared to the Control and DENV groups, suggesting that activation of DC isrelated to control of DENV." (PMID 21559444, 2011). "As RRV exposure, either to replication-competent or inactivated virus, does not induce substantial pDC death, and as the cytokine response occurs rapidly following infection, this scenario seems unlikely." (PMID 20532161, 2010). "Surprisingly, the number of total or activated (CD69+) CD4+ T cells that were elicited to the lungs of RSV infected mice did not change when cDC and pDC or cDC alone were expanded before infection." (PMID 18320041, 2008). "Therefore, to determine how changes in gene expression may regulate pDC function throughout infection we investigated the total set of DEG between the uninfected condition and all 3 infection timepoints (5361 unique genes)." (PMID 39920132, 2025). "Moreover, the pDC-dependent increase in IL-6 and TNF levels was observed only when pDCs were in direct contact with MDMs, further supporting an additive/promotive role of pDCs in this cellular response to infection." (PMID 37253946, 2023). "However, we show here that the pDC subset is not required at the time of infection, but is required at the time of treatment for FL to enhance neutrophil responses to infection, bacterial clearance, and survival after wound infection." (PMID 28228109, 2017). "Moreover, in mice, pDC depletion compromises the control of HSV-1 or HSV-2 only for systemic but not local infections." (PMID 25954804, 2015). "A recent report shows that pDC are the major IFN-I producing cells during primary SIV infection but the pDC pool is replenished by their precursors lacking IFN-I production capacity post acute phase infection." (PMID 25077616, 2014). "Indeed, the ability of mouse pDC to bind LASV GP and to release type I IFN after infection with LCMV has been recently reported, suggesting that these cells could play a crucial role in the induction of immune responses during LF." (PMID 24421914, 2014). "However, they found the levels of IFNγ between pDC depleted and control mice at the later stage of infection was not different." (PMID 24386207, 2013). "Our study evaluated pDC kinetics in bone marrow only up to 12 days post infection and it is possible that hematopoietic suppression may not be occurring at this very early stage." (PMID 19424421, 2009).
infection (continued). "Thus, circulating pDCs may not be the subsets responding to infection, which could explain why pDC activation has not been reported in most field studies." (PMID 30886619, 2019). "Thus, similarly to pDC activation by non-canonical vesicles (see Section 3.3), it is possible that incoming viral RNAs are recognized by these sensors during internalization and, thus, without the need of productive infection." (PMID 26295405, 2015). "Thus, Siglec-H downregulation might be the consequence of pDC activation primarily by means of viral PAMP transfer rather than productive infection as previously shown for other viruses." (PMID 24086137, 2013). "In addition to the difference in the duration of immune activation in pathogenic and non-pathogenic infections, some studies also suggest that the extent of pDC activation and level of type 1 IFN production in the acute phase of infection may be related to subsequent disease progression." (PMID 20937128, 2010). "Therefore, it was first hypothesized that a lack of pDC responses contributed to the failure to control viral replication early on after primary infection." (PMID 21994554, 2009). "Furthermore, recent evidence from a nonhuman primate study shows that early accumulation of pDC at the initial site of infection in the vaginal mucosa drives the affluence of CCR5+ CD4 T cells, which are targets for SIV infection at this site, ultimately favoring the systemic diffusion of the virus." (PMID 32280376, 2009). "In contrast to pDC-depleted mice, IFNAR1−/− mice infected i.v. with C. rodentium did not lose weight during infection and there was no dissemination of bacteria into spleen or liver." (PMID 31024525, 2019). "Despite this lack of pDC activation, similar to other PRRSV strains, a short but high-level systemic IFN-α response during the first week of infection was observed in pigs infected with the Lena strain." (PMID 27458429, 2016). "We show that pDC are major, but not exclusive, producers of IFN-α that mediate a marked but transient IFN-α response in lymph nodes in the acute phase of infection." (PMID 23935491, 2013). "Consistent with the prior result, Tlr7−/y pDC in infected chimeras exhibited long tracks and did not arrest while WT pDC had much shorter tracks and arrested, establishing that TLR7 signaling intrinsic to pDC, is required for them to stop during infection." (PMID 36278864, 2022). "Interestingly, an intra-vaginal challenge with HSV-2 also leads to a pDC-dependent IFN-I production, but only locally as the cytokines can be detected in the vaginal wash but not in the blood, consistent with the lack of dissemination of the infection in immunocompetent animals." (PMID 21994554, 2009).